GPRC5A (G protein-coupled receptor class C group 5 member A)
Description:
Orphan receptor. Could be involved in modulating differentiation and maintaining homeostasis of epithelial cells. This retinoic acid-inducible GPCR provide evidence for a possible interaction between retinoid and G protein signaling pathways. Functions as a negative modulator of EGFR signaling (By similarity). May act as a lung tumor suppressor.
Synonyms: PEIG-1; GPCR5A; RAI3; RAIG1; TIG1
Tractability: Antibody: UniProt places it where antibodies can reach, with high confidence; its Gene Ontology location is reachable by antibodies, with high confidence; UniProt predicts a signal peptide or a membrane-spanning region; the Human Protein Atlas places it where antibodies can reach. PROTAC: ubiquitination databases record sites on it.
Target class: Family C G protein-coupled receptor; Membrane receptor
Gene: Protein-coding gene on chromosome 12 (12,890,782 to 12,917,937, forward strand). Ensembl gene ENSG00000013588.
Subcellular location: Cell membrane; Cytoplasmic vesicle membrane
Subcellular location (Human Protein Atlas): Vesicles; Plasma membrane; Primary cilium; Primary cilium tip
Gene Ontology:
Molecular function: cadherin binding; protein binding; G protein-coupled receptor activity; protein kinase activator activity
Biological process: negative regulation of epidermal growth factor-activated receptor activity; signal transduction; G protein-coupled receptor signaling pathway
Cellular component: cytoplasmic vesicle membrane; extracellular exosome; plasma membrane; vesicle; receptor complex; membrane
Genetic constraint (gnomAD): Loss-of-function variants: 13 observed, 16.76 expected, observed/expected ratio (o/e) 0.78, 90% interval 0.5 to 1.23. The upper end of that interval is the gene's LOEUF score, 1.23, which puts it in group 5 of 6, group 1 being the genes least tolerant of losing a copy. Missense variants: 398 observed, 404.67 expected, observed/expected ratio (o/e) 0.98, 90% interval 0.9 to 1.07. Synonymous variants: 171 observed, 168.46 expected, observed/expected ratio (o/e) 1.02, 90% interval 0.89 to 1.15.
Homologues: Orthologues: chimpanzee GPRC5A (99% identical), macaque GPRC5A (89% identical), dog GPRC5A (78% identical), rabbit GPRC5A (76% identical), mouse Gprc5a (75% identical), rat Gprc5a (75% identical), pig GPRC5A (74% identical), guinea pig GPRC5A (71% identical), tropical clawed frog gprc5a (46% identical). Paralogues in human: GPRC5D (43% identical), GPRC5C (37% identical), GPRC5B (32% identical).
Diseases named in the same sentence as GPRC5A in open-access papers:
GPRC5A is named in the same sentence as 88 diseases in open-access papers, as found by Europe PMC text mining. Sharing a sentence is not in itself a finding about the gene and the disease. The quoted sentences say what the papers report.
lung carcinoma (38 papers, 2009 to 2025). "These functional data support the view that FAM189A2 acts as a negative regulator of metastatic potential in lung cancer cells and are directionally consistent with its association with the favorable early GPRC5A+ malignant program in our single−cell analyses." (PMID 41567189, 2025). "GPRC5A is dysregulated in a broad range of cancers, which indicates that it can potentially be used as a diagnostic candidate, especially in lung cancer." (PMID 30417009, 2018). "Previous study showed that GPRC5A deficiency leads to dysregulated STAT3 signaling via EGF-EGFR pathway in lung cancer." (PMID 28270740, 2017). "Taken together, these results suggest that upregulation of ceruloplasmin, lipocalin 2 and perioston are associated with development of lung cancer, and correlated with repression of GPRC5A in NSCLC." (PMID 28088789, 2017). "Gprc5a gene knockout (ko) leads to development of both spontaneous and carcinogen-induced lung cancer in mice, indicating that Gprc5a deficiency is sufficient to initiate lung tumorigenesis." (PMID 28088789, 2017). "As a matter of fact, dysregulation of GPRC5A has been associated with several cancers including lung cancer, breast cancer, colorectal cancer, and pancreatic cancer." (PMID 25621293, 2014). "Loss of the GPRC5A gene may lead to the development of spontaneous lung cancers in mice." (PMID 33788883, 2021). "Multiple studies have indicated that GPRC5A serves as an important tumor suppressor gene in lung cancer." (PMID 38634049, 2024). "Previously, expanded BASCs (SPA+ CC10+) were proposed as the cells of origin for lung cancer in the transgenic KrasG12V and the Gprc5a-KO mouse models." (PMID 38292172, 2024). "BASCs are the candidate cells of origin for lung cancer, in the KrasG12D and Gprc5a-KO mouse models." (PMID 38292172, 2024). "GPRC5A is predominately expressed in lung epithelial cells, but its expression is often lost in lung cancer." (PMID 36413416, 2023). "GPRC5A is a lung tumor suppressor and is often expressed at a low level in smoking lung cancer patients." (PMID 37486552, 2023). "For example, GPRC5A expression is reduced in lung cancer and inhibits lung tumorigenesis, while in most cancers, GPRC5A functions as an oncogene." (PMID 36735162, 2023). "Approximately half of the studies on GPRC5A have focused on the lung, and GPRC5A acts as a tumor suppressor in lung cancer with low expression." (PMID 36735162, 2023). "To determine the potential role of DNA methylation in GPRC5A repression, we examined the status of DNA methylation in 2 CpG islands at the GPRC5A promoter in lung cancer tissues and AN tissues via bisulfite sequencing PCR." (PMID 36413416, 2023). "Gprc5a-knockout (-KO) mice have normal lung development, but develop spontaneous lung cancer in later life." (PMID 36413416, 2023). "GPRC5A was downregulated (log2FC = 1.93, p = 0.0002) as previously reported in other cancers, especially in lung cancer, where it displayed a tumor suppressive role." (PMID 35203352, 2022). "MDSC number is revealed to abnormally increase in lung cancer in a Gprc5a-knockout mouse model, which promotes lung cancer metastasis regulated by enhanced prostaglandin E synthase (PTGES)/PGE2 signaling." (PMID 34689842, 2021). "Deletion of Gprc5a resulted in persistent signal transducer and activator of transcription 3 (Stat3) activation that was important for lung cancer cell survival and transformation." (PMID 33753999, 2021). "Previous research indicated that GPRC5A is considered an anti-oncogene in lung cancer and the expression level of GPRC5A in lung cancer tissue is much lower than that in normal lung tissue." (PMID 33788883, 2021). "Our previous research found that GPRC5A deficiency led to uncontrolled activation of EGFR-STAT3 in the S/TB region, and a similar phenomenon was also observed in human lung cancer." (PMID 32157214, 2020).
lung carcinoma (continued). "GPRC5A also prevents acute lung injury and lung cancer and is mainly expressed in distal, flat bronchiolar epithelium, which also express NLRP3." (PMID 32778128, 2020). "Previously, Gprc5a-ko mice were shown to develop spontaneous lung cancer in 1.5 to 2 years, and lung tumorigenesis was associated with pulmonary inflammation." (PMID 32060421, 2020). "Spontaneous lung tumor development in Gprc5a-KO mice occurs at an older age, which is in accordance with the time of human lung cancer occurrence." (PMID 32157214, 2020). "Our results are in accordance with previous studies on GPRC5A in other tumors, including head and neck squamous cell carcinoma, pancreatic cancer, lung cancer, and leukemia." (PMID 31246342, 2019). "GPRC5a was reported to be strongly expressed in the lung and is regarded as a tumor suppressor in lung cancer as well as in head and neck squamous cell carcinoma." (PMID 29949874, 2018). "Knockdown of GPRC5A correlates with STAT3 activation in cancers such as lung cancer and head and neck squamous cell carcinoma (HNSCC), pointing to a tumor suppressive role for GPRC5A." (PMID 30417009, 2018). "GPRC5A exerts a tumor suppressive role in lung cancer and GPRC5A deletion promotes lung tumor initiation and progression." (PMID 30417009, 2018). "Next, to determine how GPRC5A affects tumour progress, we analysed the correlation between GPRC5A expression levels and lung cancer patient survival." (PMID 27273304, 2016). "Understanding the underlying mechanisms of GPRC5A functions will yield new insights into lung tumorigenesis and permit development of novel therapeutic invention for restoring the tumor suppressive functions of GPRC5A in lung cancer." (PMID 25311788, 2014). "In this study, we showed that EGFR interacts with and phosphorylates GPRC5A, leading to inactivation of the tumor suppressive function of GPRC5A in lung cancer cells." (PMID 25311788, 2014). "Gprc5a– knockout mice develop spontaneous lung cancer, indicating Gprc5a is a lung tumor suppressor gene." (PMID 25311788, 2014). "All together these data suggest a role for NF-κB in lung cancer promotion in the Gprc5a-/- mice in response to bacterial induced inflammation through activation of the HIF-1α pathway and its downstream angiogenic signals." (PMID 22239913, 2012). "Notably, the Gprc5a-ko mouse lung cancer model exhibits two significant characteristics: the spontaneous development of lung tumors and a persistent state of inflammation." (PMID 39987248, 2025). "A recent study has found that cigarette smoke extract could inhibit the expression of GPRC5A in normal human lung epithelial cells and lung cancer cells, inducing the expression of WNT5a and the pathogenesis of lung cancer." (PMID 37486552, 2023). "Importantly, GPRC5A repression is found in human non–small cell lung cancer (NSCLC) samples and chronic obstructive pulmonary disease (COPD) tissues." (PMID 36413416, 2023). "Lung tumor suppressor G protein–coupled receptor, family C, member 5A (GPRC5A), is repressed in most non–small cell lung cancer (NSCLC); however, the mechanisms remain unclear." (PMID 36413416, 2023). "GPRC5A has been reported as a tumor-suppressor gene in lung cancer." (PMID 33788883, 2021). "G protein-coupled receptor family C group 5 type A (GPRC5A) is a lung cancer suppressor gene." (PMID 34689842, 2021). "In contrast, GPRC5A is generally recognized as a tumor suppressor gene in lung cancer." (PMID 33753999, 2021). "In certain circumstances, such as k-ras mutation or GPRC5A deficiency, AT2 cells can interact with the microenvironment to evolve into a subtype with a cancerous phenotype that matches that of one of the originating cell types in lung cancer." (PMID 32157214, 2020). "In GPRC5A-knock out mice, prostaglandin E2 synthase (PTGES)/prostaglandin E2 (PGE2) signaling is highly associated with tumorigenesis and metastasis and is related to immune suppression in lung cancer." (PMID 32325999, 2020).
lung carcinoma (continued). "Moreover, lung cancer patients with either low GPRC5A or high PTGES expression exhibited poor overall survival." (PMID 32060421, 2020). "GPRC5A is highly expressed in breast cancer whereas in lung cancer, it is often downregulated." (PMID 32719397, 2020). "Studies have also found that GPRC5A expression is significantly suppressed in patients with lung cancer (including adenocarcinoma, squamous carcinoma, and small cell carcinoma) and lung tissue samples from patients who smoke or have the chronic obstructive pulmonary disease (COPD)." (PMID 32157214, 2020). "To test this hypothesis, we used the same anti-correlation bioinformatics approach on the RNA datasets generated from the Gprc5a nicotine-induced lung cancer model." (PMID 30425966, 2018). "Additionally, EGFR inhibitors have been shown to be more effective in GPRC5A knockout lung cancer cells than in GPRC5A wild-type lung cancer cells, indicating that they are more suitable for lung cancer patients with lower GPRC5A expression." (PMID 30417009, 2018). "GPRC5A exhibits a promising tumor suppressive role in lung cancer." (PMID 30417009, 2018). "GPRC5A gene expression was frequently suppressed in lung cancer and HNSCC cells." (PMID 28270740, 2017). "Importantly, repression of GPRC5A has been found in most of human lung cancer including lung adenocarcinomas (ADC) and squamouse cell carcinomas (SCC)." (PMID 28088789, 2017). "Thus, targeting EGFR by RTK inhibitors will restore the tumor suppressor functions of GPRC5A in lung cancer cells." (PMID 25311788, 2014). "Thus, EGFR-mediated tyrosine phosphorylation represents a newly identified mechanism by which the tumor suppressive function of GPRC5A is inactivated in lung cancer." (PMID 25311788, 2014). "Thus, targeting receptor tyrosine kinases will be an effective in preventing and treating lung cancer by restoring the tumor suppressor function of GPRC5A." (PMID 25311788, 2014). "Therefore, the Gprc5a knockout mouse model emulates better the typical course of lung cancer development in the setting of COPD in humans who have smoked cigarette and became chronically colonized with bacteria." (PMID 22239913, 2012). "Therefore, it is likely that gene expression patterns in the NNK-exposed Gprc5a knockout mouse model closely resemble those found in human lung cancer epithelial cells." (PMID 20686609, 2010). "In addition, given the pivotal role of tobacco use in the etiology of human lung cancers, we thought that if a tobacco carcinogen were to enhance lung tumorigenesis in the Gprc5a KO mice, this model would be more relevant to the human disease." (PMID 20686609, 2010). "Given that most human lung cancers (80%) occur in ever smokers, we thought that it might be valuable to investigate the effects of exposure of Gprc5a-knockout mice to a tobacco-specific carcinogen such as NNK." (PMID 20686609, 2010). "We also provide evidence that suggests that differential gene expression patterns in NNK-induced lung carcinogenesis in the Gprc5a-knockout mouse cells may be conserved in human lung cancer epithelial cells." (PMID 20686609, 2010). "In addition, we also found the GPRC5A is down-regulated in lung tissues of pneumonia, suggesting the GPRC5A deficiency might promote the enrichment of SPA+ABCG1+ subset in S/TB region and SPA+ABCG1+might serve as markers for the early diagnosis of lung cancer." (PMID 32157214, 2020). "Importantly, tumorigenesis in Gprc5a-ko mouse lung is associated with inflammation along with persistent activation of NF-κB, EGFR, and STAT3 signaling, which resembles the pathological features in human lung cancer." (PMID 32060421, 2020). "Thus, targeting EGFR can restore the tumor suppressive functions of GPRC5A in lung cancer." (PMID 25311788, 2014).
lung carcinoma (continued). "In this study, we conducted a comprehensive reanalysis of publicly available data and employed the Gprc5a–/–/SR-IκB mouse model alongside in vitro cell experiments to elucidate the correlations between NF-κB and EAAT3 in lung cancer." (PMID 39987248, 2025). "It was shown that GPRC5A interacts with the epidermal growth factor receptor (EGFR) thereby preventing its signaling and reducing proliferation of lung cancer cells." (PMID 32719397, 2020). "We isolated Sca-1+Abcg1+cells from Gprc5a-KO mice and SPA+ABCG1+ cells from tumor samples from patients with lung cancer, respectively and injected these cells into NOD/SCID mice via the tail vein to evaluate the tumor initiation capacity of this subset." (PMID 32157214, 2020). "And repressed GPRC5A correlates with activated EGFR and STAT3 signaling in lung cancer, which explains dysregulated STAT3 induced by aberrantly activated EGFR in lung cancer." (PMID 28270740, 2017). "Together, these results indicate that endogenous EGFR can phosphorylate GPRC5A at four identified tyrosine residues (Y317, Y320, Y347 and Y350) in response to EGF stimulation in the lung cancer H1792 cells." (PMID 25311788, 2014). "The highest levels of inflammation and tumor promotion were seen in Gprc5a-/- mice exposed to both NNK and NTHi, indicating an additive role for smoke- and bacterial-induced inflammation in progression from COPD to lung cancer." (PMID 22239913, 2012). "Together, these analyses define a continuum of malignant epithelial states in lung cancer and LUAD, from proliferative and stress−adapted subpopulations dominated by Modules 8, 14 and 16 to an early GPRC5A+, stem−leaning subpopulation that preferentially engages the Module−15 signaling program." (PMID 41567189, 2025). "Hence, this specific cluster and its distinct gene expression markers (GPRC5A, NAPSA, and SLC34A2) hold promise as prognostic indicators for lung cancer, a prominent source of brain metastases." (PMID 39058687, 2024). "Some of these genes have been well characterized in lung cancer, for instance, NAPSA29 is a common prognostic marker for LUAD, and KRT18, KRT7, and GPRC5A have been reported to play important roles in tumor progression and chemoresistance in various types of cancers." (PMID 35102706, 2022). "Similarly, GPRC5A and TAGLN, two reported potential tumor suppressors in lung cancer, were also observed to be downregulated after expression of HPV16 oncogenes." (PMID 30918060, 2019). "Here we showed the role of bacterial-induced COPD-like inflammation in a background of tobacco carcinogen exposure in lung cancer promotion and progression in a mouse model with lack of Gprc5a activity." (PMID 22239913, 2012). "Such functions could be regulated by GPRC5A phosphorylation, since crosstalk of this receptor with EGFR induces GPRC5A phosphorylation and switch from tumor‐suppressive to oncogenic activities in lung cancer." (PMID 32115889, 2020). "We found that the Sca-1+Abcg1+cells from Gprc5a-KO mice and SPA+ABCG1+ cells of tumor samples from patients with lung cancer both could develop tumors in the lungs, while the Sca-1+Abcg1− and SPA+ABCG1− subsets (not P5 subset) failed to initiate tumor formation." (PMID 32157214, 2020). "GRPC5A belongs to a small subfamily of four members that are activated by retinol, the bioactive version of vitamin A. Although the role of GPRC5A is not well characterised at present, initial investigation reports a link with lung cancer, and also as a negative regulator or with adipogenesis." (PMID 31696970, 2020). "According to recent reports, the expression of GPRC5A is the highest in disease-free normal bronchial epithelia (NBE), intermediate in cancer-free lungs from patients with chronic obstructive pulmonary disease (COPD) and the lowest in patients with COPD and lung cancer." (PMID 30417009, 2018).